IL6 (interleukin 6)
Diseases named in the same sentence as IL6 in open-access papers (continued):
Sharing a sentence is not in itself a finding about the gene and the disease.
diabetes (continued). "Evidence for local up-regulation of IL-6 and IFNγ in retina in diabetes comes from studies in rats." (PMID 20856927, 2010). "Analysis of each of these variables by age showed a significant age trend for BMI, waist-hip ratio (marker of central adiposity), alcohol use, systolic blood pressure, elevated cholesterol, prevalence of diabetes, leptin, adiponectin, IL-6, bilirubin, and albumin with increasing age." (PMID 21170382, 2010). "Diabetes is also an inflammation-prone condition because hyperglycemia-induced ROS stimulates signal transduction to elaborate inflammatory cytokines, e.g. TNF-alpha, IL-1beta and IL-6, which facilitates inflammation, endothelial dysfunction, coagulation and exacerbated the severity of diabetes." (PMID 19678956, 2009). "TNF-alpha and IL-6 levels remains significantly elevated after adjustment for sex, age, left ventricular ejection function, body mass index, coronary heart disease, smoking, hypertension and diabetes mellitus with linear regression analysis." (PMID 19909503, 2009). "Furthermore, NF-kB (P < 0.01), TNF-α, and IL-6 (P < 0.05)were significantly reduced, indicating that PAItrap3 may alleviate metabolic dysfunction in diabetes by suppressing inflammatory pathways." (PMID 40575785, 2025). "Diabetes mellitus (DM) is characterized by chronic low-grade inflammation, with elevated baseline IL-1β and IL-6." (PMID 41158128, 2025). "Several studies on diabetes patients treated with conventional periodontal therapy have confirmed a positive effect on local fibroblast proliferation, together with significant reductions in serum levels of inflammatory mediators (e.g., IL-6, TNF-α), and decreased HbA1c." (PMID 40724728, 2025). "In diabetes-induced renal injury, caffeic acid protects renal function by reducing serum creatinine and blood urea nitrogen and inhibiting the production of inflammatory cytokines (such as IL-1β, IL-18, IL-6, and TNF-α) and the expression of NLRP3 inflammasome." (PMID 40909020, 2025). "The significant rise in IL-6 observed in diabetic individuals suggests that exercise-induced myokine release may foster a more favorable metabolic environment, potentially mitigating some of the adverse effects of diabetes." (PMID 40091956, 2025). "The CCS and EDS could successfully lower blood glucose, regulate lipid metabolism, lower the levels of total cholesterol (TC) and low-density lipoprotein cholesterol (LDL-C), reduce the expressions of interleukin-6 (IL-6) and interleuki n-10 (IL-10), and decrease diabetes-related liver damage." (PMID 38790786, 2024). "In addition to IL-6, several clinical factors, such as diabetes, hypertension, a previous history of coronary artery disease, and cerebrovascular accidents, were associated with elevated h-cTnT levels, highlighting the importance of identifying high-risk patients." (PMID 38271442, 2024). "A nested case-control analysis within a prospective study of 3,842 Swiss adults without baseline diabetes followed for 5.5 years on average showed that diabetes risk increased with highest vs. lowest quartile of baseline IL-6 (OR 1.58 [1.02 – 2.45]) and CRP (OR 4.63 [2.85 – 7.53])." (PMID 38665261, 2024). "Similarly, our previous study showed that after phytohemagglutinin stimulation, the PBMCs of patients with diabetes expressed lower IFNγ and IL-10 levels; however, they had higher monocyte responsiveness, which is measured based on TNFα/IFNγ and IL-6/IFNγ ratios." (PMID 39062154, 2024). "IL-6 in STZ-induced diabetes may exhibit both proinflammatory and immunoregulatory actions." (PMID 39337082, 2024). "Additionally, the levels of inflammatory biomarkers, including IL-6 and TNF-α, were found to be significantly higher in the saliva of diabetic patients, reflecting the tissue damage and systemic inflammation associated with diabetes." (PMID 39795606, 2024).
diabetes (continued). "PD is well known to be in a close pathophysiological relationship with diabetes mellitus (DM) type 2, and IL-6 is indeed a significant proinflammatory cytokine in both DM and periodontitis pathogenesis." (PMID 38396821, 2024). "The transition from prediabetes to diabetes has been linked to the presence of both pro- and anti-inflammatory indicators, including adiponectin, the recently discovered extracellular AGE-binding receptor (EN-RAGE), interleukin-6 (IL-6), IL-13, CRP, IL-18, IL-1 receptor antagonist, and neopterin." (PMID 39031306, 2024). "In addition, in diabetes, rising blood glucose levels create advanced glycation end products (AGEs) that also lead to the higher expression of proinflammatory cytokines, such as interleukin-6 (IL-6)." (PMID 36643585, 2023). "miR-204 upregulation, reduced NOX, RAGE, MMPs expression, downregulation of IKKβ/NF-κB phosphorylation, Nrf2, AdipoR1/2, JNK activation, TNF-α and IL-6, reduced macrophage infiltration, and ERK and PDX1 activation may reduce diabetes-associated CVDs and diabetic nephropathy." (PMID 37108833, 2023). "In addition, diabetic lipocalin-2 KO mice show diminished STZ-induced Iba1 overexpression by microglia, limited macrophage infiltration and decreased pro-inflammatory cytokines expression including TNF-α and IL-6, supporting a role for lipocalin-2 in diabetes-induced brain inflammation." (PMID 36869375, 2023). "The relationship between plasma IL-6 and AVF dysfunction events was further investigated in predefined subgroups stratified by the presence of diabetes mellitus (DM) and IL-6 levels, with a cut-off value defined as a median value (>2.945 pg/mL)." (PMID 36675812, 2023). "The alterations observed in the expression of Tnf-α, F4/80, Il-6, Tgf-β1, Igf-1, and BDNF could predispose to the disruption of uninjured skin homeostasis, suggesting that these alterations are the primary cause of impaired wound healing in diabetes." (PMID 36722656, 2023). "Likewise, loss of periostin suppressed diabetes-triggered upregulations of the pro-hypertrophic genes (ANP, BNP, β-MHC), pro-fibrogenic genes (Col I, Col III, α-SMA), pro-inflammtory genes (IL-1β, IL-6, TNF-α) and pro-oxidative genes (NOX2, NOX4, 12-LOX) at the mRNA levels." (PMID 37993768, 2023). "IL-6 could effectively discriminate tuberculosis patients with and without unfavorable treatment outcomes with an AUC of 0.73 (95%CI 0.66-0.80) for all participants and 0.73 (95%CI 0.64-0.83) when restricted to participants with diabetes (Figure-3)." (PMID 34711538, 2022). "Interestingly, the correlation analysis of gut microbiota with diabetes-induced intestinal inflammation showed that Deferribacteres were positively related to FBG, pro-inflammatory cytokines such as TNF-α, IL-1β, IL-6, and IL-17, which were negatively associated with IL-10 and TGF-β." (PMID 36045662, 2022). "Since oxidative stress and inflammation in the rat model of diabetes caused by streptozotocin have an important role in the progress of diabetic nephropathy, so it is necessary to evaluate several oxidative stress and inflammatory cytokine parameters such as MDA, SOD, GPx, IL-6, and TNF-α." (PMID 35685736, 2022). "More importantly, resistance training can result in significant reductions in the levels of proinflammatory cytokines, such as TNF-α and IL-6, that are produced in adipose tissue independent of weight loss in obese adults and even in patients with diabetes mellitus." (PMID 35928568, 2022). "Additionally, plasma CRP, IL-6, and lipoprotein-associated phospholipase A2 levels were significantly higher in diabetes patients with MCI compared to T2DM controls without MCI." (PMID 35682821, 2022). "In univariate analysis, prevalent CAC at baseline was associated with age, male sex, diabetes mellitus, CVD, lower diastolic blood‐pressure, estimated glomerular filtration rate (eGFR), PEW, body mass index (BMI), FRS, lower hand grip strength, lower albumin, hsCRP, IL‐6, and AVC." (PMID 35112417, 2022).
diabetes (continued). "Cases with an unfavorable treatment outcome had significantly higher concentrations of IL-6 at baseline relative to controls (0.26 log-higher concentration, 95%CI 0.17 to 0.36, p<0.001), after adjusting for markers of disease severity, pre-treatment illness duration, smoking status and diabetes." (PMID 34711538, 2022). "The effect mediated by C. sanguinolenta was not only limited to the management of diabetes mellitus but also might be effective in the prevention and treatment of diabetic complications as they decreased the levels of inflammatory cytokines, mainly IL-6, and also act as antioxidants." (PMID 36144587, 2022). "In addition, an increase in pro-inflammatory cytokines (i.e., TNF-α and IL-6) in the circulation may trigger diabetes or atherosclerosis." (PMID 35742829, 2022). "In individuals suffering from type 2 diabetes mellitus, however, the balance is tilted towards the proinflammatory side, manifested by an upregulation of proinflammatory intracellular pathways and an elevation in circulating inflammatory markers, such as C-reactive protein, IL-6, and TNFα." (PMID 35163309, 2022). "Targeting the overexpression of IL-6 effects with a monoclonal antibody against IL-6 receptor or using Janus Kinase inhibitors may be particularly helpful for treatment of COVID-19 pneumonia in diabetes in the future." (PMID 33776910, 2021). "Our study hypothesis is that the saliva inflammatory biomarkers will be higher in Type 2 diabetics and our study investigated the association between salivary levels of selected salivary inflammatory biomarkers (CRP, IL-6 and TNFα) in type 2 diabetes mellitus and glycaemic control." (PMID 33676486, 2021). "Studies have further found that patients with long-term acute myocardial infarction (AMI) have significantly higher plasma IL-6 levels than do healthy people, and their IL-6 levels are independent of risk factors such as blood pressure, diabetes, and total cholesterol." (PMID 34231707, 2021). "Furthermore, diabetes is accompanied by an inflammatory state and oxidative stress, which are characterized by elevated levels of C-reactive protein, tumor necrosis factor-alpha, interleukin-6, and reactive oxygen species." (PMID 34876114, 2021). "IL-6 has been demonstrated to be a candidate biomarker for early detection of type 2 diabetes mellitus because it promotes hepatic secretion of triglyceride, which has been suggested as a link between inflammation and the pathogenesis of type 2 diabetes mellitus." (PMID 33676486, 2021). "Nevertheless, multiple studies have reported that an elevation of Interleukin 6 (IL-6) circulating levels in T2DM adult mice is possibly linked with an expansion of α cell mass and hyperglucagonemia, suggesting that α cell proliferation in Type 1 Diabetes Mellitus (T1DM) is probably IL-6-dependent." (PMID 34502413, 2021). "In addition, oxidative stress-related cytokines (interleukin-1, interleukin-6 and tumor necrosis factor-a) could modify glucose metabolism, which may contribute to the pathophysiology of diabetes mellitus." (PMID 33926442, 2021). "In this regard, the study aimed to investigate the role of the IL-6 cytokine family (sIL-6Ra, gp130/sIL-6Rb, and IL-11) in the regulation of mitochondrial dynamics in the liver in obese patients and to assess the contribution of these cytokines to the pathogenesis of type 2 diabetes mellitus (T2DM)." (PMID 33579000, 2021). "Additionally, OPN with other reported inflammatory cytokines particularly IL-6, IL-8, IL-18, IL-1β, TNF-α, and serum CRP have been implicated in hypertension associated with diabetes via mediating the vascular effects of both angiotensin II (Ang II) and aldosterone, respectively." (PMID 34917685, 2021). "The IL-6, ferritin, C-reaction protein, and D-dimer levels were significantly increased in patients with diabetes, suggesting that a marked inflammatory cytokine storm was associated with a more pejorative prognosis compared to patients without diabetes." (PMID 33776910, 2021).
diabetes (continued). "Notably, according to animal studies, inflammatory markers such as TNF‐α and IL6 were significantly increased in diabetic mice model, indicating that diabetes could directly result in accelerating inflammation." (PMID 33694276, 2021). "Furthermore, previous studies disclosed that vitamin D might prevent the production of IL-6 and thus could assist in reducing the incidence of type 2 diabetes mellitus." (PMID 32659891, 2020). "In the CANTOS study (Canakinumab Anti-inflammatory Thrombosis Outcome Study), the blockade of IL-1β with canakinumab diminished inflammatory markers (hsCRP and IL-6) and the cardiovascular risk in atherosclerosis patients, but did not reduce the incidence of diabetes." (PMID 32471207, 2020). "However, the possible therapeutic benefit on diabetes risk of directly inhibiting the IL-6 pathway has not been directly evaluated in large trials." (PMID 33096487, 2020). "In addition, circHIPK3 silencing alleviated mechanical hyperalgesia and thermal hyperalgesia in STZ-induced diabetes rats by inhibiting neuroinflammation through inhibiting the release of IL-1β, IL-6, IL-12, and TNF-α, indicating a close relationship between circHIPK3 and inflammation." (PMID 32318575, 2020). "Gliclazide therapy has also been shown to reduce IL-6 levels in diabetics presenting with poor glucose control, and similar to metformin we speculate that changes in the IL-6/TPO axis could mediate feedback effects on platelet generation, turnover and the average size of platelets." (PMID 32754618, 2020). "In addition, in the case of IL-18 and IL-6, the increased secretion of these cytokines under the influence of LPS in the group with diabetes may be the result of the increased production of these factors in the slices under basal conditions." (PMID 31197747, 2019). "However, pilot data in 556 high risk patients with diabetes showed that canakinumab reduced hsCRP, fibrinogen, and IL-6 with no impact on atherogenic lipids." (PMID 30873416, 2019). "Given the association of nonhealing diabetic ulcers with inflammation, the altered levels of IL-6 observed during diabetes/hyperglycemia, and the close relationship of this cytokine with skin healing, it is likely that IL-6 and/or its receptor may play important roles in diabetic wound healing." (PMID 31073533, 2019). "Moreover, increased IL-6 levels can predict disease progression in patients with diabetes." (PMID 31197747, 2019). "Thus, we speculate that serum uric acid at high concentrations, when combined with other metabolic and prooxidant changes observed in diabetes, seems to enhance the proinflammatory cytokines involving IL-1, IL-6, and TNF-alpha in T2D patients." (PMID 31110596, 2019). "Furthermore, increased omentin levels had a close association with the glucose pathway by stimulating phosphorylation of Akt in muscle tissue and with IL-6 in serum, suggesting that omentin is likely to have anti-inflammatory and protective action in experimental diabetes." (PMID 30666216, 2018). "Proinflammatory cytokine IL-6 plays a central role in acute and chronic inflammatory diseases and geriatric syndromes (e.g. cardiovascular diseases, cancer, osteoporosis, chronic obstructive pulmonary disease, diabetes mellitus, Alzheimer’s disease and inflammatory bowel diseases)." (PMID 29739343, 2018). "However, the strong correlations between IL-18 and hsCRP, IL-6 and IL-1RA in patients with T2D in contrast to their absence in T1D point towards differences in the regulation and/or the pathophysiological relevance of this cytokine between both diabetes types." (PMID 29520075, 2018). "In addition, IL-6 has been associated with type II diabetes development, and as such, RLX may prove to be a beneficial therapy in diabetes management." (PMID 29346407, 2018). "Thus, increases in IL‐6 level could be recognized in the kidney that was damaged to some extent by insulin‐resistant state or diabetes." (PMID 29632818, 2018).
diabetes (continued). "IL-1β mediates the IL-6 signaling pathway, and canakinumab, a fully human monoclonal antibody targeting IL-1β, leads to a marked reduction of both, plasma levels of IL-6 and CRP, without lowering the level of low-density lipoprotein (LDL) in patients with diabetes who were at high vascular risk." (PMID 29346331, 2018). "In our study, we observed its association with diabetes mellitus, daily dose of calcium salts, left ventricular mass (but not with markers of cardiac dysfunction), and some biomarkers of inflammation or oxidative stress, such as IL-6, MDA or ADMA." (PMID 28882110, 2017). "Observed results about prevention of experimental diabetes in DP pretreated groups may suggest that purine compounds, uric acid and other volatile toxic compounds of commercial milk may suppress oral tolerance, probably via IL-6 and TGF-β cytokine effects." (PMID 28176796, 2017). "A recent study demonstrated that Lactobacillus casei CCFM419 could protect mice against diabetes involving gut microbiota, in which the levels of the inflammatory markers such as tumor necrosis factor-ɑ and interleukin-6 decreased while intestinal glucagon-like peptide-1 levels increased." (PMID 29246012, 2017). "Furthermore, the identification of these Gram-negative bacteria, and the detection of inflammatory markers, such as increased IL-6, could be used as diabetes predictive markers in overweight, obese and in genetically predisposed individuals to develop T2D." (PMID 28966614, 2017). "The established studies suggested that soluble IL-31RA might expand the range of responsive cells and tissues because of the transsignaling for IL-6; meanwhile, myocarditis had overlapping loci with diabetes and SLE, suggesting that these autoimmune diseases shared genetic traits." (PMID 28572699, 2017). "For hsCRP, IL-6 and IL-1Ra, we found no modifying effect of diabetes on any of the associations, therefore results are presented for the whole study sample combined, adjusting for diabetes." (PMID 29195493, 2017). "In clinical practice, increased levels of C-reactive protein (CRP) and IL-6 have been suggested to predict the development of type 2 diabetes mellitus (DM)." (PMID 29147465, 2017). "Furthermore, the identification of these Gram-negative bacteria, and the detection of inflammatory markers, such as increased IL-6, could be used as diabetes predictive markers in overweight, obese, and genetically predisposed individuals to develop T2D." (PMID 28966614, 2017). "Issues that reduce the inflammation (particularly, key inflammatory markers such as pro-inflammatory mediators TNFα, IL-6, IL-1β and CRP) could offer a vital public health tool to reduce the burden of diabetes and associated complications including cardiovascular diseases in the general population." (PMID 27527213, 2016). "To evaluate the influence of diabetes mellitus on IL-6 expression, we established an STZ induced diabetic cardiomyopathy model in mice and detected the expression of IL-6 in both the serum and cardiac tissue 12-week’s after DM induction." (PMID 26972749, 2016). "The absence of any significant association between the IL6 polymorphisms and diabetes in our sample may be due to our inability to differentiate T1D from T2D, or the relatively small number of cases compared to other studies." (PMID 26911440, 2016). "Evidences indicate that hyperglycemia increases circulating IL-6 and TNF-alpha levels, by an oxidative mechanism, and this effect is more pronounced in subjects with impaired glucose tolerance, suggesting a causal role for hyperglycemia in the immune activation of diabetes." (PMID 25922592, 2015). "We postulated that TTP might regulate interleukin (IL)-6 and IL-18 expression in diabetes." (PMID 26517838, 2015). "Other inflammatory cytokines participating in low grade inflammation in diabetes are IL-6 and TNF- α, with a role that is mainly associated with the risk of DM complications." (PMID 25793613, 2015).